GATA3 (GATA binding protein 3)
Diseases named in the same sentence as GATA3 in open-access papers (continued):
Sharing a sentence is not in itself a finding about the gene and the disease.
breast carcinoma (continued). "Since then, there has been growing evidence that GATA3 could serve as a relatively sensitive diagnostic marker for breast carcinomas, parathyroid tumors, trophoblastic tumors, mesonephric adenocarcinomas, paragangliomas and pheochromocytomas etc.." (PMID 28693610, 2017). "The GATA3 transcription factor is one of the most frequently mutated genes in breast cancer." (PMID 29262572, 2017). "Although the frequency of GATA3 mutation suggests an important role in breast cancer development or progression, there is little understanding of how mutations in GATA3 affect its function in luminal breast epithelial cells and what gene expression changes result as a consequence of the mutations." (PMID 29262572, 2017). "Using a combined gene set consisting of both groups of genes, we found that promoter regions with BRCA1 mutation-associated R-loops are enriched with binding sites for breast cancer-related transcription factors, such as GATA3 and FOXA1 in LP cells and SMAD2/4 and STAT6 in ML cells." (PMID 28649985, 2017). "Importantly, aberrant GATA3 expression or mutations can impact on its downstream genes, thus induce dysfunctions including tumorigenesis, such as breast cancer." (PMID 28415601, 2017). "GATA3 is a well-studied TF that has a long history of association with breast cancer." (PMID 27833659, 2016). "FOXA1 and GATA3 on the otherhand are mutated in primary breast cancer." (PMID 26884552, 2016). "GATA3 has been identified as one of the most frequently mutated genes in breast cancer." (PMID 26922637, 2016). "In addition, FOXA1 and GATA3 are frequently targeted by mutations in breast cancer, while PBX1 is rarely affected by somatic mutations (V117M and H425N, 2 out of 892 patients)." (PMID 26215677, 2015). "Moreover, TRPS1 is overexpressed in breast cancer and its expression is linked to the ER+, GATA3 and HER2 status and to the EMT-negative phenotype, as shown here for TRPS1 and Cath-D." (PMID 26183398, 2015). "Preclinical data indicate that mutations in GATA3 also affect ER binding to DNA, modulate response of breast cancer cells to estrogen signaling, could promote tumor growth and could be associated with endocrine resistance." (PMID 26467651, 2015). "Decreased expression of GATA3 in luminal breast cancer is associated with poor clinical outcome." (PMID 24504018, 2014). "GATA3 mutations in breast cancer may be associated with loss of DNA binding, aberrant nuclear localization, decrease in transactivational activity and alterations in invasiveness, but not cell proliferation." (PMID 24748983, 2014). "Here, we have initiated an attempt to address the mechanistic basis by which mutations in the transcription factor GATA3 may provide a growth advantage to breast cancer cells." (PMID 24758297, 2014). "The association of GATA3 expression levels with ERα-positive breast cancer hallmarks may be a consequence of transcriptional regulatory connections between the two TFs." (PMID 24792166, 2014). "However, mutGATA3 failed to activate IL5/GFP expression indicating that the DBD truncation associated with luminal breast cancer diminishes GATA3 activity." (PMID 25410484, 2014). "The abnormal expression of GATA3 causes luminal A-type breast cancer." (PMID 24969172, 2014). "The altered effect of mutant GATA3, in conjunction with the central role for GATA3 in the biology of breast cancer, predicts that mutation within GATA3 sequence may lead to altered gene expression patterns in patients, with possible clinical implications." (PMID 25410484, 2014).
breast carcinoma (continued). "Our findings combine to expose possible molecular mechanisms associated with breast cancer progression and suggest that typing of patients according to their GATA3 behavior may add a layer in therapeutic considerations." (PMID 25410484, 2014). "Given the presented results establishing a link between GATA3 phosphorylation and increased protein turnover, we propose that determining pSer308-GATA3 levels in breast cancer patients could be predictive of GATA3 loss." (PMID 25479686, 2014). "GATA3 mutations are frequent in breast cancer and have been classified as driver mutations." (PMID 24758297, 2014). "The GATA3 gene was recently identified as a potential tumor marker and putative tumor suppressor gene in breast cancer, whose expression may be associated with a more fvorable prognosis and prolonged disease-free survival in breast cancer patients." (PMID 24748983, 2014). "We tested whether the variation in GATA3 levels reflects loss of expression in BLBC or increased expression in luminal breast cancer." (PMID 25410484, 2014). "In breast cancer, GATA3 expression has been correlated with estrogen receptor positive (ER+/luminal) phenotypes, accounting for roughly two thirds of breast cancer cases, while loss of GATA3 expression is correlated with ER-, less differentiated, invasive breast cancer." (PMID 25410484, 2014). "Furthermore, both mechanisms exhibit extensive changes in neoplastic development in different cancer types and loss of GATA3 expression in breast cancer patients has been significantly associated with poor clinical outcome and advanced tumor disease." (PMID 24549248, 2014). "Interestingly, while HDR GATA3 mutations are spread throughout the gene, breast cancer mutations cluster around ZnF2 and C-terminal domain." (PMID 24758297, 2014). "Additionally, mutations and expression data of luminal breast cancer patients from The Cancer Genome Atlas were analyzed to characterize genetic signatures associated with GATA3 mutations." (PMID 25410484, 2014). "We thus found a range of GATA3-associated mechanisms and a signature of genes which may be involved in breast cancer development." (PMID 25410484, 2014). "Finally, GATA3 has been linked to mammary gland morphogenesis, mammary tumor differentiation and metastasis." (PMID 25033876, 2014). "Loss of GATA3 expression has been associated with a worse prognosis in breast cancer patients." (PMID 23577196, 2013). "GATA3 polymorphisms have been associated with reduced breast cancer risk." (PMID 23284679, 2012). "Apart from these biomarkers for breast cancer, mounting evidence also indicated that expressions of GATA3 and E-cadherin in breast cancer are strongly associated with ductal differentiation and a favourable prognosis, suggestive of new breast cancer biomarkers." (PMID 21934681, 2011). "Through the analysis of Kaplan–Meier survival curves it was not possible to demonstrate a significant association between GATA-3 expression and disease-free survival in this breast cancer series, which is in accordance with data from the large cohort study of Voduc and colleagues." (PMID 19549328, 2009). "In addition, other gene whose expression has been highly correlated with ERα in breast cancer encodes the transcription factor GATA-3." (PMID 19549328, 2009). "There is also tentative data showing that different polymorphisms of the GATA3 gene may associate with differential susceptibility to breast cancer." (PMID 18533032, 2008). "Parikh and colleagues (2005) suggested that GATA3 expression might be associated with responsiveness to hormone therapy in breast cancer patients." (PMID 17078870, 2006). "Notably, both low GATA3 protein (Bergen cohort I) and mRNA levels (METABRIC cohorts II–III) are significantly associated with the group of young breast cancer patients (below 40 years), with tumors more frequently having low GATA3 compared to breast cancer patients ≥40 years (p < 0.001)." (PMID 41024411, 2025).
breast carcinoma (continued). "However, due to the proliferative defects or apoptosis induced by loss of Gata3 in mammary epithelial and tumor cells, it remains elusive whether and how loss of function of Gata3 regulates EMT in breast cancer development and progression." (PMID 37353480, 2023). "The subsequent work by these authors suggested that reduced expression of the GATA3 transcription factor plays a critical role in the cellular plasticity of IINK4c-deficient luminal progenitors, resulting in an accelerated formation of basal-like mammary tumors." (PMID 38067308, 2023). "Therefore, GATA3 splice site or frameshift mutations that partially or fully alter amino acid residues of the ZnFn2 domain may have similar impacts on breast cancer properties and interrupt luminal transcriptome." (PMID 35154280, 2022). "To rule out the possibility that the differential sensitivity was derived from different genetic backgrounds of breast cancer cell lines, we asked whether overexpressing the GATA3 p.D335Gfs mutation in GATA3-wild-type cells would induce hypersensitivity against MDM2 inhibition." (PMID 35440675, 2022). "However, due to growth defects induced by long-term loss of Gata3 and apoptosis caused by acute loss of Gata3 in differentiated tumor cells 27, 35, 40, it remains elusive if Gata3 loss promotes basal differentiation in breast cancer development and progression." (PMID 34976209, 2022). "Whether and how loss-of-function of GATA3 results in basal-like breast cancers remains elusive." (PMID 34976209, 2022). "Therefore, the higher expression of ALDOB in GATA3 mutant breast cancer tumors may be caused by involved common regulatory pathways that need to be confirmed by functional and gene–gene interaction analyses." (PMID 33462316, 2021). "Research has suggested that examination of pSer308 GATA3 expression in breast cancer patients could be predictive of GATA3 loss, enabling stratification of GATA3 positive tumours, as those predicted to lose GATA3 expression would be expected to display a poorer prognosis." (PMID 33298139, 2020). "Meanwhile, another study focused on luminal breast cancer have revealed that GATA3 is frequently mutated and its levels are significantly elevated, and could mediate the transformation of normal cells into breast cancer through deregulation of BCL2, DACH1 and THSD4." (PMID 32538432, 2020). "However, it is still largely unknown how GATA3 mutations influence broader breast cancer properties such as changes in gene regulatory networks and tumor growth." (PMID 29535312, 2018). "Heterozygous mutations in GATA3, mostly frameshifts, occur in approximately 15% of primary ER+ human breast cancers, suggesting that Gata3 may function as a haploinsufficient tumor suppressor for luminal breast cancers." (PMID 29262572, 2017). "Interestingly, substantial differences in GATA3 mutation patterns have also been noted in a Chinese cohort (see Discussion), suggesting that genetic background and environmental factors play an important role in GATA3-driven breast cancer." (PMID 27588951, 2016). "Thus, GATA3 acts to prevent tumorigenesis in normal cells by reducing populations of transformation susceptible progenitor cells, while in luminal breast cancer it induces both differentiation, and, as a tumor-supporting factor, proliferation of therapy-resistant, EMT-associated, TICs." (PMID 25410484, 2014). "However, these molecular signatures suggest that molecular typing and, subsequently, prognosis and treatment considerations for breast cancer patients may require incorporation of specific GATA3 mutations." (PMID 25410484, 2014). "In addition, we demonstrated that decreased GATA3 levels are required for progestin-induced upregulation of cyclin A2, which mediates the G1 to S phase transition of the cell cycle and was reported to be associated with poor prognosis in breast cancer." (PMID 25479686, 2014).
breast carcinoma (continued). "GATA3 was identified as one of the most significantly mutated genes in breast cancer by whole-exome sequencing and GATA3 gene mutations were identified in 4 patients with luminal tumors, including 3 previously unknown frameshift mutations near the 3′-end of the coding sequence." (PMID 24748983, 2014). "While, so far, we have focused on the effects of GATA3 overexpression in cancer cells, an additional alteration to GATA3 functional activity may be associated with mutations found in a population of luminal breast cancer patients." (PMID 25410484, 2014). "Breast cancer gastric metastasis diagnosis relies on medical history, gastroscopy, and immunohistochemistry (GATA3+, CK7+, CK20-)." (PMID 42057819, 2026). "GATA3 is also highly expressed in luminal breast cancer, where it exists as both a full-length 50 kDa protein and a truncated 37 kDa isoform resulting from a frameshift mutation; the latter displays increased stability due to its prolonged half-life (>8 h)." (PMID 41495895, 2026). "TRPS1 and GATA3 immunohistochemical stains should be considered for differentiating primary from secondary breast cancer, while CDX2 is in favor of primary gastric cancer." (PMID 40936680, 2025). "Building on this foundation, our study incorporates 3.0T HR-MRI, ultrasound imaging, and GATA3 protein expression to further extend the scope of multidimensional assessment in breast cancer, particularly in tumor detection and prognostic stratification." (PMID 40881878, 2025). "In breast cancer, the ERα, along with other oncogenic TFs (e.g., GATA3 and AP-1), drives global enhancer reprogramming and the reconfiguration of transcriptional networks." (PMID 40032852, 2025). "In conclusion, we discovered that aberrant activation of DNMT3B in breast cancer regulates the methylation of the promoter region of GATA3 and can repress this gene." (PMID 40585280, 2025). "As expected, we found that the breast tumours in both groups, GATA3–METH and GATA3–LOFDEL, shared many molecular signatures associated with the aggressive properties of breast cancer." (PMID 40585280, 2025). "Although in breast cancer, GATA-3 positive expression ranges from 60% to 100% of tumor cells, its expression in metastatic breast cancer is more sensitive and has significance in the differential diagnosis of breast metastasis." (PMID 40777117, 2025). "For instance, one study demonstrated that GATA3 modulates breast cancer progression through chromatin remodeling, achieved via nucleosome eviction, nucleosome sliding, and modulation of local histone marks." (PMID 41514651, 2025). "Although many molecular signatures, especially those associated with aggressive forms of breast cancer and poor prognosis, are shared by both subtypes GATA3–METH and GATA3–LOFDEL tumours, there are also some differences." (PMID 40585280, 2025). "Assessing GATA3 expression levels can provide a molecular basis for breast cancer subtyping, help predict disease progression and evaluate prognosis, thereby offering a reference for personalized treatment strategies." (PMID 40881878, 2025). "Immunohistochemical analysis demonstrated positive staining for GATA-3, whole-cell keratin, and estrogen receptor (ER), supporting the diagnosis of breast cancer metastases to these sites." (PMID 40989696, 2025). "For instance, in breast cancer, GATA3 acts as a tumor suppressor, regulating luminal differentiation and inhibiting epithelial-to-mesenchymal transition (EMT) and metastasis." (PMID 41514651, 2025). "In breast cancer, for example, GATA3 expression has been described as an adjunctive marker linked to a poorer overall survival in triple-positive breast cancer patients." (PMID 41155227, 2025).
breast carcinoma (continued). "For instance, GATA3 is crucial for mammary epithelial cell differentiation, and it is lost during luminal breast cancer progression." (PMID 41514651, 2025). "Most reported cases involve invasive ductal carcinoma, and IHC panels typically include markers such as SYN and CgA for pheochromocytoma, and ER, PR, HER2, GATA3, and mammaglobin A for breast carcinoma." (PMID 40746928, 2025). "In breast cancer, for instance, GATA3 maintains luminal differentiation and promotes chromatin remodeling through enhancer activation." (PMID 41585508, 2025). "Taken together, our findings suggest an ER‐independent influence of GATA3 on immune responses in breast cancer." (PMID 41024411, 2025). "Potential biomarkers of statin sensitivity in BC have been proposed, and the relevance of GATA3 as a marker for response to statins in breast cancer treatment should be elaborated." (PMID 41024411, 2025). "In female breast cancer, there is a well-established correlation between GATA3 and ER expression, with GATA3 being predominantly present in ER-positive patients and associated with lower tumor grades." (PMID 39897239, 2025). "According to our results, the gene GATA3 appears to be the main target for silencing in the DNMT3B+ aggressive forms of breast cancer, with twice the frequency of deleterious somatic alterations compared to the other genes in our selection." (PMID 40585280, 2025). "In particular, East Asian breast cancers have been reported to exhibit distinct mutational patterns, including a higher prevalence of PIK3CA mutations and a lower frequency of GATA3 mutations." (PMID 41008925, 2025). "Initial studies showed that TRPS1 was not expressed in bladder cancers and therefore, TRPS1 can be considered superior to GATA3 when the differentials include bladder and breast cancers." (PMID 40025593, 2025). "In the context of breast carcinomas, GATA3 is predominantly expressed in hormone receptor-positive tumors (luminal A and luminal B) and HER2-positive carcinomas, while SOX10 serves as a hallmark stain for triple-negative (basal-like) carcinomas." (PMID 38902365, 2025). "GATA3 is crucial for the development of mammary epithelial cells, and alterations in this factor are well-known in breast cancer." (PMID 41514651, 2025). "Oestrogen receptor (ER)‐positive breast cancer cells have an inherently high level of the transcription factor GATA binding protein 3 (GATA3)." (PMID 40116537, 2025). "Overall, this study presents a novel approach to imaging diagnosis and prognosis prediction for breast cancer by integrating multidimensional assessments of 3.0T HR-MRI, ultrasound imaging, and GATA3 protein expression." (PMID 40881878, 2025). "When the frequencies of LOF mutations and CNA deletions were added together, the gene most frequently targeted for gene inactivation by these two mechanisms in breast cancer was GATA3 (8.6%)." (PMID 40585280, 2025). "In breast cancer, GATA3 drives invasive tumour cells to undergo epithelial–mesenchymal transition reversal, leading to suppression of cancer metastasis." (PMID 40585280, 2025).